ENSG00000283536 (novel protein)
Synonyms: LOC122455340
Gene: Protein-coding gene on chromosome 12 (53,241,900 to 53,242,722, forward strand). Ensembl gene ENSG00000283536.
Homologues: Orthologues: mouse Gm9918 (69% identical).